ENSG00000280371 ( gene)
Gene: Gene on chromosome 6 (41,405,819 to 41,406,561, forward strand). Ensembl gene ENSG00000280371.
Diseases named in the same sentence as ENSG00000280371 in open-access papers:
ENSG00000280371 is named in the same sentence as 181 diseases in open-access papers, as found by Europe PMC text mining. Sharing a sentence is not in itself a finding about the gene and the disease. The quoted sentences say what the papers report.
breast carcinoma (59 papers, 2003 to 2026). "Gene CENPF is a cell cycle-associated gene, and it has been identified as a marker of cell proliferation in breast cancers." (PMID 38741183, 2024). "This genome-wide association study, however, identified TYRP1 (rs41302073), a melanin synthesis regulatory gene, as a significant risk allele for breast cancer in their dataset that included African American and Barbadian women." (PMID 33659210, 2020). "Blm, the gene for Bloom syndrome, is a DNA repair gene which may play a role in breast cancer occurrence as its loss may contribute to somatic mutations and loss of heterozygosis, chromosomal instability, aneuploidy, and sensitivity to DNA damaging agents." (PMID 23967281, 2013). "Intriguingly, PDGFRL exhibits cell type-dependent roles, functioning as an oncogene in chondrocytes and as a tumor suppressor gene in breast cancer cells." (PMID 38848147, 2024). "Fisetin inhibits cell migration in mammary carcinoma by silencing the gene regulatory protein Nrf2 in the nuclear fraction, leading to reduced activity of MMP-9 and MMP-2." (PMID 38611849, 2024). "Our previous study showed that it acts as a tumor suppressor gene in breast cancer through regulation of the MEK (mitogen-activated protein kinase kinase) signaling pathway via miR-665 targeting." (PMID 39664575, 2024). "Previous studies have confirmed that FOXO3a functions as a tumor suppressor gene in breast cancer, inhibiting VEGF-A/NRP1 signaling and breast cancer metastasis by driving miRNA signatures." (PMID 38566092, 2024). "MiR-152, as a member of the miR-148/miR-152 family, is located on the chromosome 17, which functions as a tumor suppressor gene in many cancers including endometrial cancer, breast cancer and ovarian cancer." (PMID 38223603, 2023). "USP2 is a circadian rhythm-related gene that is involved in multiple biological processes, such as pressure overload-induced cardiac remodeling, breast cancer, hemophilia, and energy metabolism." (PMID 36172047, 2022). "Human breast cancer cells were transfected with p-14-3-3 sigma to overexpress the 14-3-3 sigma gene." (PMID 35890172, 2022). "Coincidentally, miR-513a-5p has been shown to possess oncogenic potential in breast cancer and glioblastoma, while in contrast act as a tumor suppressor gene in osteosarcoma tissues." (PMID 36038573, 2022). "LINC00261 was confirmed by other studies to act as a tumor suppressor gene in prostate cancer, breast cancer, pancreatic cancer and many other types of cancers." (PMID 33928038, 2021). "ARID1A is a key neoplasm suppressor gene that cooperated with CEBPα inhibited UCA1 transcription in breast cancer." (PMID 33592583, 2021). "In recent years, PCDH17 was identified as a tumor suppressor gene for breast cancer, through promoter methylation." (PMID 31772653, 2019). "In conclusions, Amot-p130 functions as a tumor suppressor gene in breast cancer, disrupting β-catenin stability by competing with Axin for binding to tankyrase." (PMID 30792381, 2019). "Recent studies also showed that estrogen up-regulate the expression of RERG a novel tumor suppressive gene which is highly expressed in ER + ve breast cancers." (PMID 29843638, 2018). "For example, in ER+ breast cancer, EglN2 is mainly regulated by estrogen and acts as a canonical estrogen inducible gene." (PMID 28036276, 2017). "Collectively, our results confirm that low levels of CSMD1 in breast cancer cells are associated with more aggressive cancer cell behavior, hence demonstrating the role of CSMD1 as tumor suppressor gene." (PMID 27764775, 2016). "SERPINB5, also known as maspin (mammary serine protease inhibitor) is a class II tumor suppressor gene identified in patients with breast cancer." (PMID 25020046, 2014). "Our results confirmed the role of PinX1 as a major tumor suppressor gene in breast cancer cell lines and provided information for further research on the molecular mechanisms of PinX1 in tumorigenesis." (PMID 24672800, 2014).
breast carcinoma (continued). "The ZNF652 (17q21.32) locus codes for a DNA binding protein thought to act as a tumor suppressor gene in breast cancer that is also co-expressed with the androgen receptor in prostate cancer." (PMID 22829776, 2012). "It was demonstrated, since its discovery as a metastasis suppressor gene that Nm23-H1 down-regulates LPA1 expression in breast cancers." (PMID 22200658, 2012). "In order to determine whether BNIP3L functions as a tumour suppressor gene in breast and/or ovarian cancer, we have analysed its expression in ovarian and breast cancer cell lines and screened all exons for mutations in a panel of primary ovarian and breast cancers." (PMID 12610513, 2003). "A recent study also found that LINC00486 may act as a tumor suppressor gene and its overexpression can inhibit the proliferation and promote the apoptosis of breast cancer tissues by suppressing miR-182–5p expression." (PMID 35399499, 2022). "On the other hand, the NRG1 gene is frequently silenced by methylation in breast cancers and NRG1 may be the principal tumor suppressor gene that leads to loss of the short arm of chromosome 8 in many breast and other epithelial cancers." (PMID 34044811, 2021). "Moreover, NEK6 also plays a role as a tumor-suppressor gene in different cancers, including thyroid cancer, gastric cancer, hepatic cell cancer, and breast cancer." (PMID 34834441, 2021). "Another potential candidate is CAV1 (caveolin-1), located at 7q31, which can act either as an oncogene (as described in bladder, thyroid, and esophageal cancers) or as a tumor suppressor gene (in ovarian, lung, and mammary tumors), depending on the tissue type or the microenvironmental influence." (PMID 34590593, 2021). "Recently, it was suggested that CDH11 acts as a tumor suppressor gene as demonstrated by its methylated and silenced status in malignant tissues such as in the nasopharyngeal, esophageal, gastric, hepatocellular carcinoma, colon, and breast carcinoma." (PMID 30691241, 2019). "Claudin-6 (CLDN6), a tight junction protein, acts as a tumor suppressor gene in breast cancer." (PMID 31412908, 2019). "Low C/EBPα levels have been observed in breast cancer, and there is epigenetic silencing in acute myelogenous leukemia which together with our data suggest a general role of C/EBPα as a tumor suppressor gene." (PMID 30599048, 2019). "Spalt like transcription factor 1 (SALL1) encodes a zinc finger transcriptional repressor, which has recently been identified as a tumor suppressor gene, whose expression was in positive correlation with CDH1 and associated with the survival of patients in breast cancer." (PMID 30233644, 2018). "Studies have shown that ERp29 may act as a tumor suppressor gene in breast cancer by regulating EMT process." (PMID 29108263, 2017). "Mapping of chromosome 3 structure in a single hTERT-repressed 21NT-#3fragment hybrid clone, revealed a 490kb region of deletion localised to 3p21.3 and encompassing the histone H3, lysine 36 (H3K36) trimethyltransferase enzyme SETD2; a putative tumour suppressor gene in breast cancer." (PMID 28977912, 2017). "Interestingly, KISS1 was first discovered as a metastasis suppressor gene and thought to play a role in suppression of metastasis of breast cancers and melanomas." (PMID 26056364, 2015). "In contrast to previous studies indicating Klotho as a putative tumor suppressor gene in human breast cancer, kidney cancer and lung cancer, our present study reveals the oncogenic function of Klotho in hepatocarcinogenesis, which is consistent with previous findings in epithelial ovarian cancer." (PMID 23516476, 2013). "Taken together, our data supported RARRES1 to be a tumor suppressor gene in breast cancer and its downregulation, by DNA methylation, CTCF binding, or by histone remodeling, might favor dissemination and survival of breast carcinoma." (PMID 22615834, 2012).
breast carcinoma (continued). "Our earlier results of NHERF1genetic alterations in human breast cancer prompted us to hypothesize that NHERF1 acts as a tumor suppressor gene in mammary gland." (PMID 18190691, 2008). "Taken together with the effects of ZFAS1 knockdown on mammary epithelial cell proliferation and differentiation, their results suggest ZFAS1 as a novel human tumor suppressor gene in breast cancer and that its dysregulation may be useful as a marker for breast cancer." (PMID 36406273, 2022). "Our findings suggest that ST5 potentially acts as a tumor suppressor gene in invasive breast cancer through regulating ERK/JNK signaling pathway and provide a novel insight for breast cancer treatment." (PMID 34395234, 2021). "Particularly melanoma, carcinoma and solid tumors have the most significant enrichment of these genes, including ABCC11 (melanoma drug resistance), SNRNP200 (retinitis pigmentosa), TRERF1 (breast cancer) and WTX (Wilms tumor gene on X chromosome, Wilms tumor)." (PMID 25523808, 2014). "Evidences suggest that GSN may act as a tumor suppressor gene, indeed, several studies showed a GSN down-regulation in human cancers including breast carcinoma." (PMID 30925779, 2019). "Interestingly, in some tumors with non-amplified MYCN (breast cancer, Wilms tumor), TSSC1 behaves as a tumor suppressor gene instead of an oncogene." (PMID 34830942, 2021).
gastric cancer (33 papers, 2014 to 2024). A primary or metastatic malignant neoplasm involving the stomach. "Previous study also reported that KLF4 was a proliferation- and metastasis-associated gene in gastric cancer." (PMID 28445396, 2017). "Thus, it was evident that miR-128, a tumor suppressor gene, is down-regulated in gastric cancer and is associated with metastatic disease." (PMID 28424413, 2017). "Accumulating evidence shows that miR-195-5p acts as a tumour suppressor gene in colorectal cancer, gastric cancer, lung adenocarcinoma, glioma, and CC." (PMID 37782756, 2023). "TSPAN5 has been shown to interact with ADAM10 and act as an oncogene in HCC and a tumor suppressor gene in gastric cancer." (PMID 37047447, 2023). "MiR-653-5p has been identified as an oncogene in PCa and gastric cancer, whereas acted as a tumor suppressor gene in cervical cancer, non-small cell lung cancer and melanoma." (PMID 34986849, 2022). "Consistently, we previously reported that miR-194 functioned as a tumor suppressor gene in gastric cancer." (PMID 36620589, 2022). "Vezatin, adherens junctions transmembrane protein (VEZT) has been identified as a tumor suppressor gene in gastric cancer." (PMID 35923577, 2022). "For example, as a tumor suppressor gene, miR-455-5p inhibited the proliferation and metastasis of gastric cancer cells by down-regulating the expression of Rab18." (PMID 34288799, 2021). "In recent years, research has indicated that miR-30c is actively involved in the regulation of malignant tumor signaling pathways and that it acts as a tumor suppressor gene in the majority of malignant tumors, such as renal cell carcinoma, colorectal cancer, gastric cancer, and breast cancer." (PMID 36180477, 2022). "A previous article testified that miR-6745 was low expressed in gastric cancer and miR-6745 overexpression reduced the growth of gastric cancer cells in vitro and in vivo, suggesting that miR-6745 might be a tumor suppressor gene in gastric cancer." (PMID 35935583, 2022). "Low expression of miR-149 in gastric cancer was detected by analyzing TCGA database and confirmed using qRT-PCR in 20 pairs of gastric cancer tissues and five gastric cancer cell lines, suggesting that miR-149 plays a role as a tumor suppressor gene in gastric cancer." (PMID 34957298, 2021). "miRNA‐646 has been reported to be down‐regulated in many human cancers and is involved in the development of many malignant tumours as a tumour suppressor gene, including colon cancer, pancreatic cancer, gastric cancer, lung cancer, osteosarcoma and clear cell kidney cancer." (PMID 32378344, 2020). "However, miR-24 was also found to be a tumor suppressor gene that inhibited gastric cancer progression by decreasing the gene expression of regenerating islet-derived family, member four." (PMID 26006243, 2015). "This indicates that the high methylation modification of PTCH1 as a tumor suppressor gene may be one of the main mechanisms of gastric cancer." (PMID 25013484, 2014). "Here we reported that ARHGAP15, a Rho GTPase activating protein, enhanced gastric cancer (GC) metastatic colonization, which was quite different from its reported role as a tumor suppressor gene in other cancers." (PMID 36802400, 2023). "In addition to the single hypoxia-related gene, the gene signature of several genes has been studied in several cancers, such as lung cancer and gastric cancers, which could achieve a more reliable prognostic value than the single one." (PMID 35789607, 2022). "Suppressor anaphase-promoting complex domain containing 2 (SAPCD2), also known as p42.3 or C9orf140, is a cell cycle-dependent gene which was first identified in the gastric cancer (GC) cell line, BGC823." (PMID 32055236, 2020). "This suggested that NAG-1 may function as a tumor-suppressor gene in gastric cancer carcinogenesis." (PMID 24348798, 2014).
gastric cancer (continued). "As a well-known negative regulator of cell cycle progression, CHFR was regarded as a tumor suppressor gene and hypermethylation in CHFR gene promoter were frequently observed in multiple cancer types, such as colorectal cancer and gastric cancer." (PMID 37024798, 2023). "As a tumor suppressor gene, lncRNA ZNF667-AS1 significantly hinders the propagation, metastasis, and angiogenesis of gastric cancer cells by promoting the expression of E-cadherin and inhibiting the expression of N-cadherin and VEGFA." (PMID 35813862, 2022). "The reduced expression of ATBF1 was consistent with that in other cancers, such as prostate cancer and gastric cancer, which suggested ATBF1 as a tumor suppression gene." (PMID 36476423, 2022). "PARK2 is frequently deleted in human tumors and is a tumor suppressor gene, although the precise role of PARK2 in gastric cancer requires more detailed investigation." (PMID 28603669, 2017). "Previous studies demonstrated that miR-760 may act as a tumor suppressor gene in non-small cell lung cancer (NSCLC), colorectal cancer and gastric cancer." (PMID 36153332, 2022).
colorectal cancer (31 papers, 2008 to 2026). A primary or metastatic malignant neoplasm that affects the colon or rectum. "Axin2, as a target gene of the Wnt signaling pathway, was previously categorized as a tumor suppressor gene in a small fraction of colorectal cancers harboring APC gene mutations." (PMID 35875099, 2022). "Myosin IIA is considered a tumor-suppressing gene, but recent studies have reported that high protein expression is associated with poor overall survival in colorectal cancer, suggesting that myosin IIA may have an oncogenic role." (PMID 36139553, 2022). "NDST4 was previously identified as a putative tumor-suppressor gene in human colorectal cancer and its genetic loss might be related to the colorectal cancer progression." (PMID 29297280, 2017). "In addition, a previous study on colorectal cancer showed that methylation of another DNA repair gene, MGMT, is also linked to MSI." (PMID 23414134, 2013). "miR-342 has also been demonstrated to act as a tumor suppressor gene that inhibits the growth of colorectal carcinoma by regulating aberrant DNA hypermethylation." (PMID 36310619, 2022). "miR‐138‐5p was weak‐expressed in some kinds of cancers: It acted as a tumor suppressor gene in colorectal cancer to imped cell proliferation, and aerobic glycolysis served as a competing endogenous RNA." (PMID 34586647, 2021). "S100A4 is a well-known metastasis-inducing gene in colorectal cancer and S100A4 inhibition for therapeutic intervention is suggested." (PMID 31581665, 2019). "The heart and neural crest derivatives expressed 1 (HAND1), belonging to the basic helix-loop-helix family of transcription factors, is showed to be a tumor suppressor gene in colorectal cancer." (PMID 31565069, 2019). "On one hand IGFBP7 has recently been described as a tumour suppressor gene in colorectal cancer and was shown to induce senescence in cells harbouring oncogenic BRAF, whereas on the other hand IGFBP7 was shown to have oncogenic properties in gliomas." (PMID 20579385, 2010). "Previous research shown that miR-384 may act as a tumor suppressor gene in colorectal cancer 53, oral squamous 54 and prostate cancer." (PMID 39132166, 2024). "Integral membrane protein 2C (ITM2C), a member of the ITM protein family, is considered a tumor suppressor gene in colorectal cancer and may inhibit tumor cell growth and division." (PMID 38531846, 2024). "Sirt1 has also been reported to be an autophagy-related gene in colorectal cancer." (PMID 38214831, 2024). "miR-338-3p has been found to function as a tumor suppressor gene in colorectal cancer, and can be used as a downstream target gene for a variety of lncRNAs to function as oncogenes to regulate biological characteristics of colorectal cancer cells, including LINC0052510." (PMID 35156520, 2022). "Finally, miR-637 has been reported to be a tumor suppressor gene in diverse human cancers, such as gastric, ovarian and colorectal cancers." (PMID 32211330, 2020). "This is consistent with the role of CDX2 as a tumor-suppressor gene in colorectal cancer." (PMID 25847407, 2015). "Moreover, ENO2 is a glycolysis-related gene that has been described to play an important role in tumorogenesis of colorectal cancers." (PMID 18694510, 2008). "Therefore, we hypothesize that Egr-1 regulate the expression of NGX6 gene in colorectal cancer as a tumor suppressor gene." (PMID 25029911, 2014). "In colorectal cancer, FHL1 has been reported to be a tumor suppressor gene by negatively regulating the Wnt/β-catenin signaling pathway." (PMID 40831931, 2025). "It serves as a candidate colorectal tumor suppressor gene and suppresses cell proliferation and WNT/β-catenin pathway in colorectal cancer cells." (PMID 35524260, 2022).
colorectal cancer (continued). "The metastasis-inducing gene MACC1 is a newly identified gene and its expression is a prognostic indicator for colorectal cancer metastasis." (PMID 22838389, 2012).